ENSG00000260234 (CLRN1 and FAM188B2 readthrough transcript)
Gene: Protein-coding gene on chromosome 3 (150,882,997 to 150,941,743, reverse strand). Ensembl gene ENSG00000260234.
Genetic constraint (gnomAD): Missense variants: 77 observed, 68.3 expected, observed/expected ratio (o/e) 1.13, 90% interval 0.94 to 1.36. Synonymous variants: 22 observed, 25.09 expected, observed/expected ratio (o/e) 0.88, 90% interval 0.63 to 1.25.